LINC02428 (long independently transcribed non-coding RNA 2428)
Gene: Long non-coding RNA gene on chromosome 4 (103,255,788 to 103,454,667, forward strand). Ensembl gene ENSG00000248740.
Diseases named in the same sentence as LINC02428 in open-access papers:
LINC02428 is named in the same sentence as 1 disease in open-access papers, as found by Europe PMC text mining. Sharing a sentence is not in itself a finding about the gene and the disease.
LINC02428 shares sentences with these, for which no sentence is quoted: tumor (1 paper).